PDGFD (platelet derived growth factor D)
Description:
Growth factor that plays an essential role in the regulation of embryonic development, cell proliferation, cell migration, survival and chemotaxis. Potent mitogen for cells of mesenchymal origin. Plays an important role in wound healing. Induces macrophage recruitment, increased interstitial pressure, and blood vessel maturation during angiogenesis. Can initiate events that lead to a mesangial proliferative glomerulonephritis, including influx of monocytes and macrophages and production of extracellular matrix (By similarity).
Synonyms: SCDGF-B; IEGF; SCDGFB; MSTP036
Tractability: Antibody: UniProt places it where antibodies can reach, with high confidence; its Gene Ontology location is reachable by antibodies, with high confidence; UniProt predicts a signal peptide or a membrane-spanning region. PROTAC: ubiquitination databases record sites on it.
Gene: Protein-coding gene on chromosome 11 (103,907,189 to 104,164,379, reverse strand). Ensembl gene ENSG00000170962.
Subcellular location: Secreted
Subcellular location (Human Protein Atlas): Golgi apparatus; Vesicles; Predicted to be secreted
Pathways (Reactome):
Signal Transduction: Signaling by PDGF
Gene Ontology:
Molecular function: platelet-derived growth factor receptor binding; growth factor activity
Biological process: platelet-derived growth factor receptor signaling pathway; positive regulation of cell migration; positive regulation of cell population proliferation; positive regulation of ERK1 and ERK2 cascade; positive regulation of phosphatidylinositol 3-kinase/protein kinase B signal transduction; cellular response to hydrogen peroxide; cellular response to platelet-derived growth factor stimulus; cellular response to transforming growth factor beta stimulus; positive regulation of fibroblast proliferation; positive regulation of glomerular mesangial cell proliferation; positive regulation of monocyte extravasation; positive regulation of smooth muscle cell chemotaxis; positive regulation of smooth muscle cell proliferation
Cellular component: endoplasmic reticulum lumen; extracellular region; Golgi membrane; membrane
Genetic constraint (gnomAD): Loss-of-function variants: 28 observed, 41.44 expected, observed/expected ratio (o/e) 0.68, 90% interval 0.5 to 0.93. The upper end of that interval is the gene's LOEUF score, 0.93, which puts it in group 3 of 6, group 1 being the genes least tolerant of losing a copy. Missense variants: 429 observed, 454.75 expected, observed/expected ratio (o/e) 0.94, 90% interval 0.87 to 1.02. Synonymous variants: 166 observed, 166.31 expected, observed/expected ratio (o/e) 1, 90% interval 0.88 to 1.13.
Gene-disease validity (ClinGen):
ClinGen rates the evidence that PDGFD causes each of these diseases.
pulmonary arterial hypertension (autosomal dominant): Limited. Pulmonary arterial hypertension (PAH) is a group of diseases characterized by mean pulmonary artery pressure >20 mmHg and elevated pulmonary arterial resistance leading to right heart failure.
Homologues: Orthologues: chimpanzee PDGFD (100% identical), macaque PDGFD (98% identical), rabbit PDGFD (92% identical), guinea pig PDGFD (87% identical), rat Pdgfd (87% identical), pig PDGFD (86% identical), mouse Pdgfd (85% identical), tropical clawed frog pdgfd (70% identical), zebrafish pdgfd (60% identical). Paralogues in human: PDGFC (41% identical), CNTNAP3 (20% identical), CNTNAP3B (20% identical), CUBN (19% identical), CNTNAP4 (19% identical), CNTNAP5 (18% identical), CNTNAP2 (16% identical), NRP1 (16% identical), NRP2 (16% identical), CNTNAP1 (15% identical), F8 (15% identical), HEPHL1 (15% identical), and 23 more.
Diseases named in the same sentence as PDGFD in open-access papers:
PDGFD is named in the same sentence as 117 diseases in open-access papers, as found by Europe PMC text mining. Sharing a sentence is not in itself a finding about the gene and the disease. The quoted sentences say what the papers report.
prostate carcinoma (20 papers, 2008 to 2024). A carcinoma that arises from epithelial cells of the prostate gland. "PDGFD was found to be associated with tumor development in a variety of malignancies of epithelial origin, such as cholangiocarcinoma, prostate cancer, breast cancer, ovarian cancer, colon cancer, laryngeal cancer, renal cancer, and so on." (PMID 38652223, 2024). "PDGFD downregulation was associated with lower proliferation levels not only in CRC but also in prostate cancer." (PMID 36362041, 2022). "Prostate cancer cells with an EMT phenotype induced by PDGFD displayed CSC features, including increased expression of SOX2, NANOG, OCT4, and Notch-1, and enhanced sphere-forming ability and rapid tumor growth in vivo." (PMID 30227608, 2018). "Four SNPs in three genes (COL4A3, PDGFD and ELK3) were associated with prostate cancer aggressiveness in both the CGEMS and Moffitt groups with a p-value less than 0.05." (PMID 23593148, 2013). "Men with the CC genotype in rs488753 (PDGFD) were more likely to develop aggressive prostate cancer than those with the CT and TT genotype (OR = 1.47, p-value = 0.035 for CGEMS; OR = 1.45, p-value = 0.031 for Moffitt)." (PMID 23593148, 2013). "There are several reports on involvement of other EMT markers eg. platelet-derived growth factor-D, hypoxia-inducible factor-1α and zinc finger enhancer binding protein 1 in prostate cancer." (PMID 20534149, 2010). "The POU1F1-derived tumors have 499 exclusive proteins that participate in events such as Platinum drug resistance (AKT3, BCL2 and GSTT2) and Prostate cancer (FGFR1, IGF1R and PDGFD) among others." (PMID 33261069, 2020). "The PDGFD protein level was determined to be an independent prognostic factor in gastric cancer while PDGFD protein levels failed to predict a recurrence in prostate cancer." (PMID 33918816, 2021).
breast carcinoma (13 papers, 2013 to 2024). "Another study also showed that PDGFD can activate CXCR4 to promote lymphatic metastasis in breast cancer." (PMID 35509844, 2022). "PDGFD was reported to be associated with epithelial-mesenchymal transition (EMT) and stem cells in a breast cancer cell line, where it was also associated with tumor growth." (PMID 36362041, 2022). "Further study revealed that platelet-derived growth factor-D contributes to aggressiveness of breast cancer cells by up-regulating Notch and NF-κB signaling pathways." (PMID 28978076, 2017). "Over-expression of PDGFD in mouse or human breast cancer cell significantly increased cell proliferation while silencing PDGFD expression decreased proliferation and increased apoptosis." (PMID 25108500, 2014). "High PDGFD protein levels also positively correlated with a higher T stage and positive lymph node status in colorectal cancer while a high PDGFC protein level has been shown to correlate with positive lymph node status in breast cancer." (PMID 33918816, 2021).
glioma (8 papers, 2014 to 2025). A benign or malignant brain and spinal cord tumor that arises from glial cells (astrocytes, oligodendrocytes, ependymal cells). "Since PDGFD and PDGFRB were associated with genes involved in glioma tumor cell invasion and migration, we next examined the relationship between tumor expression of PDGFD or PDGFRB and LGG patient survival." (PMID 34539622, 2021). "In support of this, PDGFD and PDGFRB were positively correlated with a three-gene signature (TGFBI, IGFBP3, and CHI3L1) associated with glioma tumor cell invasion and migration and poor patient survival." (PMID 34539622, 2021). "In addition, HCMV-infected gliomas exhibited significantly increased PDGFD and Ki67 levels and intratumor vascularization than mock-infected controls." (PMID 37058447, 2023).
ovarian carcinoma (8 papers, 2014 to 2024). A malignant neoplasm originating from the surface ovarian epithelium. "Intriguingly, the expression levels of PDGF ligands in tumor cells were inconsistent, as PDGFA and PDGFB stained strongly, whereas PDGFC and PDGFD stained weakly in ovarian cancer tumor cells." (PMID 36199822, 2022). "Several studies have reported that PDGFD overexpression is an independent predictor of chemotherapy resistance in ovarian cancer and colorectal carcinoma, consistent with our results." (PMID 34016089, 2021). "Furthermore, the deregulation of other downregulated genes following RBPMS knockout, including PDGFD, TES, CARD16, and KNF521, has been linked to the progression of many cancer types, and the role of these genes in the ovarian cancer setting should be investigated." (PMID 35008958, 2022). "Despite lower expression in ovarian cancer than in normal tissues, patients with higher PDGFD, PDGFRA, and PDGFRB also had worse OS, PFS, and PPS in ovarian cancer." (PMID 36199822, 2022). "In ovarian cancer, PDGFB (P < 0.05), PDGFD (P < 0.05), PDGFRA (P < 0.001), and PDGFRB (P < 0.001) had a significant positive correlation with macrophage M2 infiltration, and PDGFA had a negative association with macrophage M1 infiltration (P < 0.01)." (PMID 36199822, 2022). "ROC analysis also demonstrated that PDGFD (AUC = 0.995), PDGFRA (AUC = 1.000), and PDGFRB (AUC = 0.997) could be a single significant parameter to discriminate between normal and tumor tissues of ovarian cancer." (PMID 36199822, 2022).
cholangiocarcinoma (7 papers, 2019 to 2024). A carcinoma that arises from the intrahepatic biliary tree (intrahepatic cholangiocarcinoma) or from the junction, or adjacent to the junction, of the right and left hepatic ducts (hilar cholangiocarcinoma). "PDGFD can also bind PDGFRB and activate cancer-associated fibroblasts (CAFs) that play crucial roles in modulating cholangiocarcinoma development." (PMID 37838792, 2023). "For example, cholangiocarcinoma cells recruit CAFs by secreting platelet-derived growth factor D (PDGF-D), boosting cell migration through PDGFR-β, RHO-GTPase, and c-JUN N-terminal kinase (JNK) pathway activation." (PMID 35409206, 2022). "Platelet-derived growth factor-D (PDGF-D) secreted by cholangiocarcinoma cells could stimulate surrounding fibroblasts to produce VEGF-C and VEGF-A, resulting in the expansion of lymphatic vasculature and tumor cell intravasation." (PMID 36185262, 2022). "In vitro and murine xenograft experiments showed that CAFs express Platelet Derived Growth Factor Receptor β (PDGFR-β), and that cultured cholangiocarcinoma cells secrete the PDGFR-β ligand Platelet Derived Growth Factor-D (PDGF-D) resulting in fibroblast migration and recruitment." (PMID 30819129, 2019).
gastric cancer (7 papers, 2014 to 2024). A primary or metastatic malignant neoplasm involving the stomach. "The increased expression of PDGFD was linked to tumor progression, immune infiltration, and prognosis of patients with gastric cancer." (PMID 35509844, 2022). "Furthermore, we also created a gene signature and a nomogram based on the immune genes highly associated with PDGFD and differentially expressed in gastric cancer to predict the prognosis of STAD." (PMID 35509844, 2022). "Finally, we used the eight immunoregulatory genes coexpressed with PDGFD in gastric cancer and the TCGA dataset to create an immune-associated signature made up of two genes (CXCR4 and TAP1)." (PMID 35509844, 2022). "Our study also found that in the gastric cancer cell that overexpressed circ-0007707, the expression of miR-429 decreased while the expression of PDGFD increased." (PMID 35509844, 2022). "We evaluated how PDGFD mRNA undergoes certain chemical modifications during translation in gastric cancer, resulting in higher levels of PDGFD protein in cancer tissues." (PMID 35509844, 2022). "It has opened up new avenues for research into the effects of PDGFD on gastric cancer immunotherapy." (PMID 35509844, 2022). "Kaplan-Meier survival analysis was selected to analyze the intervention of PDGFD on the survival time of patients with gastric cancer." (PMID 35509844, 2022). "RT-PCR revealed that expression of circ-0007707 and miR-429 in gastric cancer cells and normal mucosal cells was significantly different, and western blot revealed that PDGFD is differentially expressed in gastric cancer tissues." (PMID 35509844, 2022). "PDGFD was demonstrated to be mediated in the progression of gastric cancer as an immune-related gene." (PMID 35509844, 2022). "circ-0007707 regulates the expression of PDGFD through the circ-0007707/miR-429/PDGFD pathway, in order to elucidate how this pathway mediates the progression and metastasis of gastric cancer and its effect on the survival time of gastric cancer patients." (PMID 35509844, 2022). "We also confirmed how PDGFD regulates immune infiltration in gastric cancer using the TIMER database." (PMID 35509844, 2022). "This demonstrated that circ-0007707/miR-429/PDGFD pathway could mediate the development of gastric cancer by regulating the tumor microenvironment of gastric cancer." (PMID 35509844, 2022). "The signature constructed based to the downstream immune gene of PDGFD could be selected as an important prognostic factor in gastric cancer." (PMID 35509844, 2022). "In this study, we identified PDGFD, a targeted gene of circ-0007707/miR-429/PDGFD pathway, which could regulate 10 important immune cells in the tumor microenvironment of gastric cancer and was also involved in the expression of several immune genes." (PMID 35509844, 2022). "However, further research should clarify the molecular mechanism of the circ-0007707/miR-429/PDGFD pathway, and interestingly, the expression of PDGFD mRNA and protein in gastric cancer shows two opposing trends." (PMID 35509844, 2022). "In conclusion, circ-0007707/miR-429/PDGFD regulates immune infiltration, and immunomodulatory genes may be the key mechanism and a new target for immunotherapy in gastric cancer." (PMID 35509844, 2022). "TISIDB revealed five immune subtypes related to gastric cancer; we discovered that PDGFD has higher expression in the TGF-B subtype compared to the other four subtypes, indicating that PDGFD may act as an immunomodulatory factor in the TGF-B subtype." (PMID 35509844, 2022). "In gastric cancer, the circ-0007707/miR-429/PDGFD pathway had a differential expression." (PMID 35509844, 2022). "In this study, we constructed the circ-0007707/miR-429/PDGFD pathway which could mediate the development of gastric cancer and patients' prognosis." (PMID 35509844, 2022).
gastric cancer (continued). "This suggests that circ-0007707 could absorb miR-429 to control the expression of PDGFD in gastric cancer, and the circ-0007707/miR-429/PDGFD pathway mediated the progression of gastric cancer." (PMID 35509844, 2022). "Furthermore, gastric carcinoma patients with a high level of PDGFD expression will have a poor prognosis." (PMID 35509844, 2022). "Moreover, platelet-derived growth factor-D contributes to aggressiveness of gastric cancer cells by up-regulating Notch and NF-κB signaling pathways." (PMID 28423627, 2017). "Furthermore, a multifactorial regression analysis of 376 advanced osteosarcoma patients found that the CD4+/CD8+ is an independent prognostic factor for osteosarcoma.PDGFD played a regulatory role in gastric cancer and pancreatic cancer by interfering with the tumor microenvironment." (PMID 38652223, 2024).
glioblastoma (7 papers, 2017 to 2025). The most malignant astrocytic tumor (WHO grade IV). "Other drugs such as chlorpromazine, echinomycin, fenofibrate, and R50922/R59949 inhibit glioblastoma growth via several mechanisms, including the blockade of dopamine signaling, interference with the HIF1α-PDGFD/PDGFRα-AKT pathway, and the induction of apoptosis." (PMID 38893207, 2024). "We analysed gene expression of the PDGF system (PDGFA, PDGFB, PDGFC, PDGFD, PDGFRA, PDGFRB) in 36 GBMs studied on Ivy Glioblastoma Atlas Project." (PMID 29127351, 2017).
atherosclerosis (6 papers, 2013 to 2024). A disease characterized by the build-up of fatty material and calcium deposition in the arterial wall resulting in partial or complete occlusion of the arterial lumen. "Many of the genes identified are implicated in the regulation of SMC plasticity during atherosclerosis, including PDGFD, COL4A1/2, CDKN2B and CDKN2A/p19ARF." (PMID 23874238, 2013). "PDGFD encodes for a platelet derived growth factor with implication in atherosclerosis." (PMID 35246263, 2022). "Among these genes, only STAU1, SERGEF, and PDGFD are known to be associated with atherosclerosis." (PMID 33381146, 2020). "Several studies have demonstrated that PDGFD plays a vital role in atherosclerosis development." (PMID 33381146, 2020). "However, biological investigation of a role for PDGFD in atherosclerosis has yet to be conducted." (PMID 36792607, 2023).
myocardial infarction (6 papers, 2016 to 2024). Gross necrosis of the myocardium, as a result of interruption of the blood supply to the area, as in coronary thrombosis. "Increased PDGF signaling via SMC Pdgfrb in Lrp1-KO mice increased aortic atherosclerosis, and loss-of-function PDGFD variants are associated with a reduced risk of myocardial infarction." (PMID 39531316, 2024). "The only associations with other variants within PDGFD of genome-wide significance (p<5 × 10−8) have been reported with coronary artery disease and myocardial infarction (rs974819, rs2128739, and rs2019090), with linkage disequilibrium 0·03 or less." (PMID 29551627, 2018). "In addition, results of an animal study showed that mRNA expressions of PDGFA, PDGFB, PDGFC, PDGFD and PDGFRs exhibited different changes in the infarcted rat heart in the early and late stages after myocardial infarction." (PMID 39569832, 2024). "They found that the expression of PDGFA, PDGFD and PDGFRB in the infarcted myocardium were increased after myocardial infarction, whereas PDGFB and PDGFC mRNAs were reduced and protein levels at infarcted myocardium were all significantly reduced in the early stage of myocardial infarction." (PMID 39569832, 2024).
asthma (5 papers, 2018 to 2024). "Proteins TCN2,TNFRSF1B and C10orf54 were positively associated with the development of asthma (B>0); proteins PDGFD,INHBC and ANXA7 were negatively associated with the development of asthma (B<0)." (PMID 39318474, 2024). "Our findings suggest that genetic variation in the PDGFD gene locus increases the risk of adrenal suppression in children and adults who use corticosteroids to treat asthma and COPD, respectively." (PMID 29551627, 2018). "A polymorphism in the PDGFD gene locus was identified in a cohort of children with asthma in a genome-wide association study and found to be associated with adrenal suppression." (PMID 29551627, 2018). "Four out of ten of the PDGFD variant carriers have additional diagnoses of other pulmonary fibrotic and/or vascular fibrotic diseases including bronchopulmonary dysplasia, emphysema, asthma, and one patient (E010173) with both mixed pulmonary valve disease and peripheral vascular disease." (PMID 33971972, 2021). "Although PDGFB is associated with alterations in airway remodelling in asthma, a link to PDGFD has not been made." (PMID 29551627, 2018). "We considered whether PDGFD genotype might affect asthma or COPD severity, and hence corticosteroid dose used in the patients." (PMID 29551627, 2018). "Taken together, these data suggest that patients with adrenal suppression attributable to PDGFD variants do not have more severe asthma or reduced response to ICS." (PMID 29551627, 2018).
pancreatic cancer (5 papers, 2012 to 2024). "In agreement with the oncogenic function of PDGFD in human malignancies, PDGFD overexpression has been detected in a variety of cancers including prostate, lung, renal, ovarian, brain, and pancreatic cancer." (PMID 30227608, 2018).